CD8A (CD8 subunit alpha)
Diseases named in the same sentence as CD8A in open-access papers (continued):
Sharing a sentence is not in itself a finding about the gene and the disease.
colon carcinoma (continued). "In the present study, we demonstrated that [64Cu]NOTA-CD8a was able to detect treatment-induced changes in CD8a+ infiltration in murine CT26 colon tumors following a common preclinical combination treatment protocol." (PMID 32086762, 2020). "Our study can serve as a theoretical basis for the combined evaluation of IDO1 and CD8A expression, and as a promising prognostic and predictive biomarker for colon cancer." (PMID 33425745, 2020). "Given the strong evidential basis for efficacy of IDO1 and CD8+ T cell infiltration in tumor progression and immune escape of colon cancer, we further explored the prognostic relevance of IDO1 expression in combination with CD8A expression." (PMID 33425745, 2020). "The combination of VEGFR-2 inhibitors with PD-1 immunotherapy has been shown to enhance effective blood perfusion, alleviate hypoxia, promote infiltration of CD8a+ T lymphocytes into the tumor, and exert synergistic anti-tumor effects on the mouse colon cancer model." (PMID 38395884, 2024). "Although contribution of the differential TME components to patient prognosis remains elusive, our current study proposed that CAF activation represented by COL8A1 in addition to CTL activation reflected by CD8A are critical determinants of prognosis in colon cancers." (PMID 38557819, 2024). "Our analysis of colon cancer patient data indicated that tumors with high SIX4 expression were significantly enriched in the Inflammatory Response pathway and that SIX4 expression was positively associated with CD8A expression." (PMID 37888903, 2023). "Furthermore, it is demonstrated that CD8a density lacks prognostic significance in the FAP intensity-low subset of colon cancer." (PMID 33153037, 2020). "Moreover, the IDO1/CD8A stratification was identified as an independent prognostic factor of overall survival (OS) and a useful predictive biomarker in colon cancer." (PMID 33425745, 2020). "Therefore, we examined whether prognostic significance of IDO1 could be dependent on CD8A gene expression levels in colon cancer." (PMID 33425745, 2020). "Drawing on the results showing that the higher MSI proportion and E-Cadherin downregulation were particularly enriched in group IV*, we explored whether there was an association between the CMS and colon cancer risk subgroups stratified by IDO1 and CD8A expression using the TCGA data." (PMID 33425745, 2020). "In the present study, the findings suggest that IDO1/CD8A stratification has additional and independent prognostic implications beyond CMS classification, which may contribute to improved risk-stratification in colon cancer." (PMID 33425745, 2020). "Consistent with the report, in primary colon cancer, high IGFBP3 expression showed significantly poorer prognosis than low IGFBP3 expression (p = 0.0028) totally differently from CD8A." (PMID 38557819, 2024). "In this study, the average expressions of CD8A, CD8B, GZMA, GZMB, and PRF1 genes were used to represent level of CTL in colon cancers." (PMID 38327746, 2024). "To evaluate which immune cell populationswere mediating antitumor efficacy, we administered depletion antibodiesspecific for CD4, CD8α, or colony stimulating factor-1 receptor(CSF1R) to MC38 colon carcinoma-bearing mice prior to starting polymertherapy." (PMID 36313164, 2022). "For C7 (CD8+ TEMRA/TEFF), there were 359 DEGs between colon cancer and rectal cancer, such as HSPA1L and IL7R were up-regulated, while CD8A and CTSW were down-regulated in colon cancer compared to that in rectal cancer." (PMID 33584715, 2020). "Transcriptome analysis of 57 advanced colon cancer samples revealed that one of the non-T cell inflamed subtypes (group 4) had low expression of CD8a, IFNG and GZMB with high expression of SCD1 and CTNNB1(β-catenin) and its downstream molecules including VEGFA and TCF12." (PMID 35793868, 2022).
colon carcinoma (continued). "In the right-side tumor, when patients were grouped based on VEGFA expression, we found a twofold decrease in CD8A expression, and observed a negative correlation (r = −0.3903, *p = 0.0441) between VEGFA and CD8A expression in right-side colon cancer." (PMID 30042763, 2018). "Interestingly, we observed the lowest OS in group IV*, even though it had high levels of CD8A, whereas Group III* had the most favorable outcomes for colon cancer with higher CD8A expression in the absence of IDO1 expression (P = 0.032)." (PMID 33425745, 2020).
autoimmune disease (635 papers, 2005 to 2026). A disorder resulting from loss of function or tissue destruction of an organ or multiple organs, arising from humoral or cellular immune responses of the individual to their own tissue constituents. "We designed a custom T cell panel to detect CD3ε, CD4, CD8α and FoxP3 in murine tissue to characterize T cell infiltrates in murine syngeneic tumors and autoimmune disease models." (PMID 38605049, 2024). "It is known that CD8a-SIRPα+ cDCs mainly induce CD4+ T cell responses, which is an important effector T cell population in autoimmune diseases, whereas CD8a+SIRPα- cDCs has greater ability to induce a CD8+ T cell response." (PMID 34093583, 2021). "Collectively, the deficiency of Clec4A4 aggravates the development of T-cell-mediated autoimmune disease through the excessive activation of CD8α− cDCs." (PMID 27068492, 2016). "Further, we demonstrated that the therapeutic effect of GM-CSF was primarily mediated through the mobilization of CD11c+CD8α− DCs that could stimulate the expansion of Tregs in vivo and suppress autoimmune disease through increased IL-10 production." (PMID 30297856, 2018). "We suggested that the CD11c+CD8α− DC subset may play a role in the amelioration of autoimmune diseases through Treg expansion and increased IL-10 production." (PMID 30297856, 2018). "CD8α− DCs from GM-CSF treated mice that produce significantly lower levels of pro-inflammatory cytokines IL-12 and IL-1β compared to the DCs from control mice can induce and/or expand Foxp3+ Tregs and suppress autoimmune diseases." (PMID 21779356, 2011). "Moreover, the increased/decreased numbers of ZBTB16-expressing CD8+ T cells in patients with metastatic melanoma/autoimmune disease, respectively, suggest that these cells, akin to their murine CD8α+CD8β-TCRαβ+ counterparts, may be capable of suppressing the inflammatory responses in vivo." (PMID 34349770, 2021).
pancreatic cancer (606 papers, 2003 to 2026). "The IHC staining of PDAC tissue samples showed an increased expression of VISTA, CD68, and CD8A in pancreatic cancer tissues." (PMID 38357542, 2024). "In pancreatic cancer, the number of CD8α-positive cells tended to be higher in EXT1 score-1 and EXT1 score-2 cases than those in EXT1 score-0 cases, and there was a significant difference between EXT1 score-0 and EXT1 score-1 cases." (PMID 36809261, 2023). "In pancreatic cancer, the number of CD8α-positive cells tended to increase with the increase in the score, with significant differences observed between EXT1 score-0 and EXT1 score-1 cases." (PMID 36809261, 2023). "In a pancreatic cancer model, tumour-derived type I IFN activates DCs and CD8α+ DCs engulf apoptotic tumour material and cross-present tumour-associated antigen to naïve CD8+ T cells." (PMID 36106115, 2022). "In addition, IHC analysis showed significantly higher expression of CD4, CD8a and PD-1 in orthotopic pancreatic cancer sections in the THM + αPD-1 group compared with the vehicle group, THM and αPD-1 groups." (PMID 40756353, 2025). "However, there was a significant increase in CD68 expression and a notable reduction in CD8A expression in pancreatic cancer." (PMID 38357542, 2024). "Conversely, the present findings have demonstrated as a proof of principle that tripartite treatment allow infiltration of CD4 and CD8a and other immune activators including effector T-cells and turns the pancreatic tumor to a hot tumor which is more responsive to tripartite treatment." (PMID 32326142, 2020). "This analysis revealed that in pancreatic tumors generated by HY24409 cells, either GR knockdown or mifepristone treatment significantly increased the abundance and activity of CTLs, as gauged by CD8 (a marker of CTLs) and granzyme B (a marker of CTL activity), respectively." (PMID 34873175, 2021). "Approximately 40% to 70% of CD8A+ T lymphocytes co-expressed PDCD1 and/or HAVCR2 in both IF and TC, independently of the neoadjuvant chemotherapy, suggesting that T cytotoxic lymphocytes are exhausted in the pancreatic cancer microenvironment." (PMID 32645996, 2020).
Autoimmunity (564 papers, 2007 to 2026). The occurrence of an immune reaction against the organism's own cells or tissues. "Earlier, we have shown that GM-CSF-exposed CD8α− DCs that express low levels of pro-inflammatory cytokines IL-12 and IL-1β can induce Foxp3+ Tregs leading to suppression of autoimmunity." (PMID 21779356, 2011). "Earlier, we have shown that mice treated with GM-CSF carry large numbers of CD8α− tolerogenic DCs with the ability to induce and/or expand antigen specific Foxp3+ Tregs and suppress autoimmunity." (PMID 21779356, 2011). "For example, L-DC in san/san animals show an up-regulation of CD8α and MHC-II expression, possibly reflecting activation of cells because of the constant inflammatory state induced by autoimmunity." (PMID 24251878, 2013). "Based on our current findings, we suggest that a subset of the CD11c+CD8α− DCs express OX40L and this subset may be the critical “tolerogenic” DC subtype capable of selectively expanding Tregs and thus suppressing autoimmunity." (PMID 30297856, 2018).
gastric cancer (557 papers, 2004 to 2026). A primary or metastatic malignant neoplasm involving the stomach. "Results unveiled that CD8A expression was significantly higher in normal tissues compared to gastric cancer tissues and exhibited a strong correlation with HIC1." (PMID 40279559, 2025). "Then, PD-L1 and CD8A mRNA expression was analyzed using gastric cancer data from the TCGA database, confirming a positive correlation." (PMID 30003113, 2018). "The correlation analysis between Treg cell signature genes (CD4, CD25 and FOXP3) and CD8A in The Cancer Genome Atlas (TCGA) database containing 415 gastric cancer samples revealed that the expression of CD4, CD25 and FOXP3 was positively correlated with CD8A expression respectively." (PMID 37208608, 2023). "In addition, TCGA whole exome sequencing dataset analyses showed that ERBB2‐nonamplified gastric cancer cases harbored higher mutation numbers, CD8A expression levels, and CYT scores." (PMID 37325934, 2023).
Sepsis (452 papers, 2007 to 2026). Sepsis is defined as life-threatening organ dysfunction caused by a dysregulated host response to infection. "Further, ST2 deficiency is strongly associated with decreased percentage of inflammatory CD11c+CD8α+ cells as well as IL-12 expressing CD11c+ dendritic cells during sepsis." (PMID 30001716, 2018). "Based on the discussion and analysis, it is reasonable to assume that IL7R, GZMA and CD8A possess significant potential value in the diagnosis and prediction of sepsis." (PMID 39654893, 2024). "A similar finding was found in HIV-infected patients with sepsis, who showed overexpression of genes involved in cytotoxic T-cell signaling (CD8A, CD8B)." (PMID 34497613, 2021). "Levels of CD14+ CD16+ monocytes, and Th, Tc + CD8α+ γδ T lymphocytes, and Treg lymphocytes decreased in time due to sepsis in both experimental groups." (PMID 32117276, 2020). "Although the half-life of mRNA has a significant impact on protein formation, it does not affect the conclusion of the data analysis in this article that IL7R, GZMA and CD8A may serve as the attractively potential molecular biomarkers for sepsis." (PMID 39654893, 2024). "However, IL7R, GZMA and CD8A may serve as the attractively potential molecular biomarkers for sepsis." (PMID 39654893, 2024). "Dot plot of these genes in sepsis single-cell data revealed the CD8+ T cell exhaustion subcluster (TS3 with high CD8+ T cell markers CD8a, CD8b, and exhaustion markers PDCD1 and CTLA4)." (PMID 37077915, 2023). "HIV positive sepsis patients in both ICU cohorts showed overexpression of genes involved in granzyme signaling (GZMA, GZMB), cytotoxic T-cell signaling (CD8A, CD8B) and T-cell inhibitory signaling (LAG3), compared to HIV negative patients." (PMID 26871709, 2016). "Cytotoxic T-cell signaling (CD8A, CD8B) and T-cell inhibitory signaling (LAG3) were overexpressed in HIV patients both during sepsis and in asymptomatic HIV infection." (PMID 26871709, 2016). "CD4, CD8A, CD28, CD2, CD3E as T cell surface active molecules play important roles in the immune response process; among them, the roles of CD4 and CD8 T lymphocytes in sepsis have been widely recognized." (PMID 39654893, 2024). "In HIV negative sepsis patients, a reduction in CD8A and CD8B is consistent with immune suppression, which is considered an integral part of the host response to sepsis, and also involves enhanced apoptosis of CD8 T cells." (PMID 26871709, 2016). "Principal component analysis of GZMA, GZMB, CD8A, CD8B, KLRD1, PRF1 and LAG3 gene expression revealed 81% explained variance for the first principal component considering HIV negative and HIV positive sepsis patients." (PMID 26871709, 2016).
malaria (441 papers, 2004 to 2026). Malaria is a serious and sometimes fatal disease caused by a parasite that commonly infects a certain type of mosquito which feeds on humans. "Studies in mice have shown that CD8α+ dendritic cells (DC), which are responsible for the activation and induction of malaria-specific CD8+ T cells, accumulated at higher rates in the liver after infection than after RAS-immunization." (PMID 36298634, 2022). "At the first stage, anti-CLEC9A antibodies were used to target malaria antigens to CD8α+DCs to efficiently prime malaria-specific CD8+ T cells." (PMID 31379818, 2019). "This has been demonstrated that CD8α+ DCs are responsible for the activation and induction of malaria LS-specific CD8+ T cells in response to RAS vaccination and confers the protective immunity in the liver." (PMID 29472929, 2018). "In CM, it was found that dendritic cells (CD8α+ DCs) are responsible for malaria antigen presentation to CD8+ T cell." (PMID 27708543, 2016). "Because our results indicated a critical role for LN-resident DCs in CD8+ T cell responses against malaria sporozoites, we designed a 6-color panel to discriminate between CD8α+ and CD11b+ LN-resident DCs on stained LN sections." (PMID 25658939, 2015). "Since the activation of malaria LS-specific CD8+ T cells is also shown to be critically dependent on the CD8α+ DCs, we wanted to determine whether the inoculation of Inf." (PMID 29472929, 2018). "CD8α+ DC are critical for generating immunity to blood-stage infection and recently the human DC subset equivalent, BDCA3+ DC, have been implicated in severe malaria in humans." (PMID 24854165, 2014). "Given the vital role for CD8α+ DCs in the presentation of malaria antigens, and the unique expression of pattern recognition receptors among different DC subsets, it will be interesting to determine whether adjuvant activation of CD8α+ DCs can provide better protection after ID immunization." (PMID 25658939, 2015). "These cells may be the counterpart of murine CD8-α+ DCs, which are known to cross-present parasite antigens and mediate effective CTL responses against blood stage P. berghei in a murine model of malaria." (PMID 21483827, 2011).
lymphoma (432 papers, 1992 to 2026). A malignant (clonal) proliferation of B- lymphocytes or T- lymphocytes which involves the lymph nodes, bone marrow and/or extranodal sites. "They demonstrated that stimulation of CD8+ T cells through the CD8α:MyD88 construct improved control of A20 lymphoma in mice." (PMID 40948803, 2025). "For example, CTL019, which is the most widely used CAR in CD19+ leukemia and lymphoma treatment, has a CD8α hinge, while CD19RCD28 CAR uses a modified IgG4 hinge and Fc region, and also has a hinge-deleted version." (PMID 28288656, 2017). "For example, upregulated proteins such as HLA-DRB1, CD22, CD74, and CD8A are consistent with established roles in lymphoid malignancies and oncogenic signaling, supporting prior studies identifying CD74 as a diagnostic and therapeutic target in lymphomas." (PMID 41035678, 2025). "Other specific feline antibodies (anti-CD4, anti-CD8α, anti-CD8β) can be used to detect additional epitopes and define the immunophenotype of lymphomas, but their routine clinical application is limited by the fact that formalin-fixed samples cannot be used as frozen sections are required." (PMID 30305106, 2018).
HIV-1 infection (414 papers, 2004 to 2026). The type species of lentivirus and the etiologic agent of acquired immunodeficiency syndrome (AIDS). "Understanding the mechanisms that underlie this requirement for CD8α+ cell depletion at the time of infection will be a critical step toward the development of a pathogenic mmHIV-1 model of HIV-1 infection." (PMID 39459950, 2024). "An alternative or additional possibility is that NK cells, which are also profoundly depleted by CD8α antibody administration due their high surface expression of CD8α in macaques, play a major role in controlling HIV-1 infection in PTMs." (PMID 39459950, 2024). "Concretely, enhanced lipophagy leads to fuel mitochondrial metabolism due to glutaminolysis and restores protective CD8A T-cell immunity during persistent HIV-1 infection in an IL-21-dependent manner." (PMID 35514981, 2022). "In our own work, we have derived an adapted mmHIV-1 infectious molecular clone, stHIV-A19, capable of recapitulating each these key features of HIV-1 infection, but only in animals that receive cell-depleting CD8α antibody administrations at the time of virus inoculation." (PMID 39459950, 2024).
AIDS (407 papers, 2001 to 2026). A syndrome resulting from the acquired deficiency of cellular immunity caused by the human immunodeficiency virus (HIV). "After screening a number of infectious molecular clones isolated from passage recipients that were CD8α-depleted and presented a pathogenic infection course, a molecular clone designated stHIV-A19, derived from the first animal that progressed to clinical AIDS, was selected for future work." (PMID 39459950, 2024). "In animals treated with a cell-depleting CD8α antibody at the time of infection, stHIV-A19 maintains chronically elevated plasma viral loads with progressive CD4+ T-cell loss and the development of acquired immune-deficiency syndrome (AIDS)-defining clinical endpoints." (PMID 39459950, 2024). "However, in the absence of CD8α+ cell depletion, no mmHIV-1 model has yet displayed high levels of chronic viremia or AIDS-like pathogenesis." (PMID 39459950, 2024).
diabetes (379 papers, 2003 to 2026). "In the combined analysis of genes unique to DR and those in common with diabetes mellitus at the threshold of <0.05, we identified C2, C4A, CD8A, HLA-DRB5, and HLA-DQA2, which have been associated with lymphocyte-mediated immunity (FDR 2.96 × 10−2)." (PMID 38791494, 2024). "Either CD8α or β2-microglobulin-deficient NOD mice do not develop diabetes." (PMID 34526989, 2021). "For example, it has been reported that the number of splenic CD8α+ DCs and CD8α− DCs in NOD mice is low as compared to those of the diabetes-resistant B10.BR and C57BL6J mice." (PMID 21647406, 2011).